ZNF557 (zinc finger protein 557)
Description:
May be involved in transcriptional regulation.
Synonyms: MGC4054
Tractability: PROTAC: ubiquitination databases record sites on it.
Gene: Protein-coding gene on chromosome 19 (7,069,701 to 7,087,968, forward strand). Ensembl gene ENSG00000130544.
Subcellular location: Nucleus
Subcellular location (Human Protein Atlas): Intermediate filaments; Nucleoplasm
Pathways (Reactome):
Gene expression (Transcription): Generic Transcription Pathway
Gene Ontology:
Molecular function: DNA-binding transcription factor activity, RNA polymerase II-specific; RNA polymerase II transcription regulatory region sequence-specific DNA binding; sequence-specific double-stranded DNA binding
Biological process: regulation of transcription by RNA polymerase II; regulation of DNA-templated transcription
Cellular component: nucleus
Genetic constraint (gnomAD): Loss-of-function variants: 12 observed, 15.66 expected, observed/expected ratio (o/e) 0.77, 90% interval 0.49 to 1.24. The upper end of that interval is the gene's LOEUF score, 1.24, which puts it in group 5 of 6, group 1 being the genes least tolerant of losing a copy. Missense variants: 452 observed, 502.46 expected, observed/expected ratio (o/e) 0.9, 90% interval 0.83 to 0.97. Synonymous variants: 197 observed, 193.42 expected, observed/expected ratio (o/e) 1.02, 90% interval 0.91 to 1.15.
Homologues: Orthologues: chimpanzee ZNF557 (99% identical), macaque ZNF557 (80% identical), Drosophila melanogaster CG3281 (26% identical), Drosophila melanogaster CG2712 (25% identical), Drosophila melanogaster Phs (20% identical). Paralogues in human: ZNF558 (73% identical), ZNF891 (43% identical), ZNF266 (42% identical), ZNF778 (41% identical), ZNF805 (40% identical), ZNF555 (40% identical), ZNF264 (39% identical), ZFP90 (39% identical), ZNF19 (38% identical), ZNF599 (38% identical), ZFP37 (38% identical), ZNF25 (38% identical), and 50 more.
Diseases named in the same sentence as ZNF557 in open-access papers:
ZNF557 is named in the same sentence as 2 diseases in open-access papers, as found by Europe PMC text mining. Sharing a sentence is not in itself a finding about the gene and the disease.
ZNF557 shares sentences with these, for which no sentence is quoted: cancer (1 paper); infectious disease (1).